SRGN (serglycin)
Diseases named in the same sentence as SRGN in open-access papers (continued):
Sharing a sentence is not in itself a finding about the gene and the disease.
multiple myeloma (continued). "Following the observation that serglycin can regulate the protein cargo of myeloma-derived exosomes, we studied the effect of SRGN exosomes and SRGN-null exosomes on tumor and host cell behavior." (PMID 29088739, 2017). "Our findings, therefore, indicate that elimination of serglycin from myeloma cells eliminates specific exosomal proteins that are capable of activating critical biological processes in target cells." (PMID 29088739, 2017). "Taken together, our findings suggested that depletion of serglycin from myeloma exosomes markedly reduces their impact on tumor and host cell behavior." (PMID 29088739, 2017). "Studies have shown that the core protein of serglycin from myeloma cells can bind to proteases like MMP-9 (matrix metalloproteinase-9) and MMP-13." (PMID 29088739, 2017). "Mass spectrometry analysis of exosomal proteins identified significantly fewer protein components within exosomes derived from serglycin-knockdown myeloma cells than within exosomes from control cells." (PMID 29088739, 2017). "Serglycin was detected in exosomes derived from cell culture supernatants of human myeloma cell lines and serum of myeloma patients." (PMID 29088739, 2017). "In the present study, we showed an important role of the CSPG serglycin in regulating the protein cargo and functions of myeloma-derived exosomes." (PMID 29088739, 2017). "Expression of serglycin has been demonstrated in a variety of lymphoma, myeloma, mastocytoma, and thymoma cells." (PMID 24455486, 2014). "In leukocytes, platelets, myeloma, and endothelial cells, serglycin contains CS chains that are mainly sulfated at C4 of N-acetyl-galactosamine (CS-4)." (PMID 24455486, 2014). "In contrast to the affinity to C1q, serglycin from MDA-MB-231 cells showed a lower affinity for MBL than serglycin isolated from the CAG myeloma cell line (KD = 1.9×10−8 M)." (PMID 24205138, 2013). "Serglycin is constitutively secreted by multiple myeloma cells and aggressive nasopharygeal cancer cells." (PMID 24205138, 2013). "The disaccharide composition was similar to that of CS chains attached on serglycin secreted by myeloma cells that also carried predominantly 4-sulfated disaccharides (up to 93%)." (PMID 24205138, 2013). "Furthermore, it has been found that serglycin exists in the exosomes derived from all human myeloma cell lines." (PMID 34722637, 2021). "Hence, serglycin in myeloma cells helps generate exosomes enriched with protein cargo that, when released into the tumor microenvironment, deliver their cargo to nearby or distant cells and thereby promote myeloma progression." (PMID 29088739, 2017). "However, a mechanistic understanding of the extracellular role of serglycin in myeloma pathobiology remains incomplete." (PMID 29088739, 2017). "Purushothaman and Toole found that serglycin knockdown in myeloma cells reduced tumor growth." (PMID 26694746, 2015). "Tumors formed by these myeloma cells where the expression of serglycin had been knocked down grew smaller and had a less expanded vasculature than the tumors derived from the parental cell line with a higher serglycin expression." (PMID 25978773, 2015). "It has been established that serglycin secreted by myeloma cells inhibits complement." (PMID 24205138, 2013). "Therefore serglycin inhibits specifically the classical and the lectin pathways without influencing alternative pathway activity, showing a biological activity similar to that of serglycin isolated from multiple myeloma cells." (PMID 24205138, 2013). "Therefore, further studies are required to understand whether modulating the anionic charge density on the CS chains of serglycin by silencing CHST11 expression myeloma cells may be an alternative approach to target myeloma exosomes." (PMID 29088739, 2017). "By Western blotting we could detect serglycin in exosomes from most of the myeloma patients." (PMID 29088739, 2017). "In addition we have also shown that myeloma-derived serglycin can bind to CD44." (PMID 29088739, 2017).
multiple myeloma (continued). "To determine if serglycin is present in exosomes that are released by myeloma cell lines, we purified exosomes from the conditioned medium of OCIMy5, CAG, and RPMI 8226 human myeloma cells using the gold standard ultracentrifugation method." (PMID 29088739, 2017). "A role for serglycin in regulating tumor vasculature has previously been suggested by studies of HCC patient material and in an in vivo xenograft model of multiple myeloma." (PMID 25978773, 2015). "Serglycin synthesized and secreted by human acute monocytic leukemia cell line THP1 as well as serglycin isolated from myeloma cells forms complexes with proform of MMP9 (proMMP9) in vivo and in vitro." (PMID 24455486, 2014). "EVs derived from myeloma cells that contain serglycin enhance macrophage migration more effectively than EVs lacking serglycin, following their uptake by the macrophages." (PMID 40443670, 2025). "We found that serglycin is required for maintaining the protein cargo of myeloma-derived exosomes, but not required for their biogenesis." (PMID 29088739, 2017). "In functional assays, exosomes from serglycin-knockdown cells failed to induce an invasive phenotype in myeloma cells and failed to promote migration of macrophages." (PMID 29088739, 2017). "Earlier, lack of CD44-expression in EBV-positive or EBV-negative BL cell lines, up-regulation of serglycin and CD44 in EBV+ BL cells, down-regulation of syndecan-1/CD138 in EBV-infected multiple myeloma cells and fibronectin and collagen in multiple myeloma patients have already been reported." (PMID 26527314, 2015). "Targeting of serglycin with siRNA in human myeloma cells decreased cell adhesion in vitro, tumour cell growth in vivo and vascularization when injected subcutaneously into immunocompromised CB17 SCID mice, suggesting an essential role for serglycin in tumour growth and vascularization." (PMID 27223472, 2016).
glioma (9 papers, 2017 to 2024). A benign or malignant brain and spinal cord tumor that arises from glial cells (astrocytes, oligodendrocytes, ependymal cells). "Mast cells infiltrate the glioma microenvironment and secrete high levels of serglycin, and the process is associated with poor survival." (PMID 35494005, 2022). "The present investigation reveals serglycin as a potential prognostic marker for glioma and demonstrates an association with the extent of MC recruitment and glioma progression, uncovering potential future therapeutic opportunities for patients." (PMID 28445977, 2017). "SRGN-expressing glioma cells after co-culture with mast cells further enhance their expression of SRGN, CD44, CXCL-10, CXCL-12 and TNFα as well as EMT-related genes ZEB-1 and vimentin." (PMID 38672477, 2024). "Serglycin is also expressed in glioma, where the cross-talk of activated astrocytes with glioma cells enhances serglycin production." (PMID 37762403, 2023). "In other tumor types, serglycin has been confirmed to promote metastatic tumor growth, and in vitro observations of human glioma tumor cells have shown increased release of the glioma stem cell marker CD44 mediated by serglycin." (PMID 38275375, 2023). "This demonstrates a key role for serglycin in glioma progression, and demonstrates how serglycin, either via induction by an inflammatory response or by direct secretion by immune cells is of major importance for cancer progression." (PMID 35494005, 2022). "Co-culture of mast cells with glioma cells induces the expression of serglycin, CD44, ZEB1, vimentin, CXCL10, CXCL12, and TNF-α in glioma cells and IL-6 and CXCL1 in mast cells, creating an inflammatory milieu that induce glioma cell aggressiveness." (PMID 35494005, 2022). "Suppression of serglycin in LN-18 shSRGN mutant cells results in retarded glioma proliferation, migration and invasive potential." (PMID 34409033, 2021). "In conclusion, we showed elevated expression of serglycin in a large cohort of human high-grade glioma TMAs and demonstrated a correlation between glioma grade and serglycin expression level." (PMID 28445977, 2017). "Serglycin expression is positively correlated with MC accumulation in tissue microarrays (TMAs) of a large cohort of human high-grade glioma tissues." (PMID 28445977, 2017). "We performed tissue analysis of serglycin expression in human low-grade (astrocytomas, oligoastrocytomas and oligodendrogliomas grade II, n = 87) and high-grade glioma (anaplastic gliomas and glioblastomas, n = 101) TMAs." (PMID 28445977, 2017). "In this study, we explored the expression of serglycin in human glioma and its correlation with survival and immune cell infiltration." (PMID 28445977, 2017). "Histological analysis in our study reveals that serglycin is expressed in human glioma and the level of expression is increasing with glioma grade." (PMID 28445977, 2017). "We demonstrate that serglycin is expressed in glioma and that increased expression predicts poor survival of patients." (PMID 28445977, 2017). "We further analyzed expression of genes involved in glioma progression, to investigate the effect of increased serglycin expression in the glioma cells upon GC-MC co-culture." (PMID 28445977, 2017). "In conclusion, these findings indicate the importance of infiltrating MCs in glioma by modulating signaling cascades involving serglycin, CD44 and ZEB1." (PMID 28445977, 2017). "The present study provides evidence that serglycin can serve as a potential prognostic marker and has detrimental effects in MC infiltrated glioma microenvironment that requires further mechanistic investigations." (PMID 28445977, 2017). "Analysis of serglycin expression in a large cohort of low- and high-grade human glioma samples reveals that its expression is grade dependent and is positively correlated with mast cell (MC) infiltration." (PMID 28445977, 2017).
glioma (continued). "Considering the positive correlation between MC number and serglycin expression in TMAs and our previous studies on MC recruitment to glioma, we postulate that serglycin expression modulated by MCs can support glioma progression." (PMID 28445977, 2017). "We found a positive correlation between MC numbers and serglycin expression in human high-grade glioma tissues implying MCs as a major serglycin source." (PMID 28445977, 2017). "We show that serglycin can promote aggressiveness in glioma by increasing the expression of ZEB-1 and vimentin." (PMID 28445977, 2017). "High-grade glioma demonstrated significantly higher expression of serglycin in comparison to low-grade glioma." (PMID 28445977, 2017). "According to the authors, these observations suggest that serglycin released by mast cells may support and further promote glioma cell progression and spread." (PMID 38275375, 2023). "Serglycin expression is elevated in astrocyte-glioma co-cultures." (PMID 34409033, 2021). "Hence we conclude that serglycin acts both as a modulating factor as well as one of the contributing factors in MC – glioma cell crosstalk." (PMID 28445977, 2017). "The present investigation reveals serglycin as a potential prognostic marker for glioma." (PMID 28445977, 2017). "Moreover, serglycin expression in patient-derived glioma cells is significantly increased upon MC co-culture." (PMID 28445977, 2017). "Also serglycin both from the glioma cells and MCs, via its interaction with CD44, can enhance growth, survival and differentiation of the cancer cells." (PMID 28445977, 2017). "Hence we believe that MC infiltration in high-grade glioma tissue can induce the aggressiveness of the glioma cells even further presumably as orchestrated by serglycin." (PMID 28445977, 2017). "Here we demonstrate that serglycin is expressed in glioma and predicts poor survival of patients." (PMID 28445977, 2017). "Considering the abundance of serglycin in high-grade gliomas and increased serglycin expression in glioma cells after GC-MC co-culture, we decided to further analyze the high-grade glioma TMAs for potential correlation between serglycin expression and markers related to tumor aggressiveness." (PMID 28445977, 2017). "We found that SRGN is overexpressed in GBM cells upon interaction with MCs and that secreted serglycin can thereby stimulate aggressive phenotypes of the glioma cells through autocrine signaling pathways." (PMID 28445977, 2017). "Statistical analysis of the expression of serglycin and ZEB1 in high-grade glioma showed a positive correlation." (PMID 28445977, 2017). "We postulate that increased expression of serglycin, as a main interacting partner for CD44, upon co-culture with MCs induces the CD44 expression on glioma cells to initiate a bidirectional signaling between CD44 and its surroundings." (PMID 28445977, 2017). "The expression of SRGN in the brain has not been well characterized, although it has been reported to increase in experimental autoimmune encephalomyelitis in mice and in glioma." (PMID 33070392, 2021). "Indeed, high-grade glioma TMAs immunostaining for ZEB1 revealed abundant expression of this protein, as well as a positive correlation between ZEB1 and serglycin levels (ρ < 0.01)." (PMID 28445977, 2017). "Although there are studies investigating proteoglycans as therapeutic targets in the brain TME there is no population-based study of tissue morphology and serglycin expression in glioma." (PMID 28445977, 2017). "In addition, the expression of serglycin and ZEB-1 is positively correlated in high-grade glioma." (PMID 28445977, 2017).
lung carcinoma (9 papers, 2015 to 2025). "In both breast and lung cancer tissues, SRGN was downregulated compared to normal adjacent tissues and correlated with inconsistent clinical outcomes." (PMID 41476965, 2025). "We have previously shown that SRGN is frequently overexpressed in lung cancer and its upregulated expression correlates to poor prognosis." (PMID 31898491, 2020). "Studies report significantly elevated SRGN expression in breast and lung cancer cell lines, as compared to colon and gastric cancer cell lines." (PMID 28445977, 2017). "In primary non-small cell lung cancers, SRGN is overexpressed by both carcinoma and stromal cells, and SRGN has been shown to induce lung cancer cell stemness and promote NSCLC cell migration, invasion and metastatic colonization." (PMID 29221141, 2017). "SRGN has also been identified as the topmost differentially enriched protein in plasma-derived extracellular vesicles in lung adenocarcinoma patients, suggesting a potential role of SRGN to serve as a biomarker for lung cancer." (PMID 31898491, 2020).
glioblastoma (8 papers, 2017 to 2026). The most malignant astrocytic tumor (WHO grade IV). "Serglycin (SRGN) has been found overexpressed and secreted in glioblastoma (GBM), associated with tumorigenic signaling and poor prognosis." (PMID 42041528, 2026). "In glioblastoma, serglycin works in an autocrine manner, and suppression of serglycin potently reduces their malignant properties, pro-neoplastic signaling, and stemness, and evokes astrocytic differentiation." (PMID 35494005, 2022). "SRGN is also a mediator of cell stemness and glioblastoma to astrocytic differentiation." (PMID 36358747, 2022). "In oesophageal squamous cell carcinoma (ESCC) and glioblastoma (GBM), SRGN can indirectly upregulate the expression of MMP2/MMP9 by activating the ERK pathway, TGF‐β signalling, or the CXCLs/CXCR2 axis, thereby enhancing tumour invasion and metastasis." (PMID 41410182, 2025). "Serglycin (SRGN) is a pro-tumorigenic proteoglycan expressed and secreted by various aggressive tumors including glioblastoma (GBM)." (PMID 38672477, 2024).
hepatocellular carcinoma (7 papers, 2015 to 2025). A malignant tumor that arises from hepatocytes. "This indicates that high expression of SRGN is closely associated with an immune activation status in hepatocellular carcinoma." (PMID 41476965, 2025). "At the single-cell level, our analysis revealed that the significantly elevated expression of SRGN in HCC cells was associated with multiple hepatoma conditions or when liver tumors infiltrated blood vessels, in comparison to solitary liver tumor cases." (PMID 40384866, 2025). "SRGN is overexpressed in a number of cancers and elevated cellular SRGN has been correlated with poor survival and recurrence in nasopharyngeal and hepatocellular carcinomas." (PMID 29221141, 2017). "Additionally, in a clinical study of patients with hepatocellular carcinoma (HCC), high expression of serglycin correlates with a poor prognosis." (PMID 25978773, 2015).
acute myeloid leukemia (6 papers, 2012 to 2022). Acute myeloid leukemia (AML) is a group of neoplasms arising from precursor cells committed to the myeloid cell-line differentiation. "In other words, SNHG3 promotes the growth of acute myeloid leukemia cells by regulating the miR-758-3p/SRGN axis, providing a new therapeutic direction for the treatment of AML." (PMID 33292213, 2020). "For example, in acute myeloid leukemia, high expression of SNHG3 enhances cell proliferation and inhibits cell apoptosis by acting as a miRNA sponge for miR-758-3p to enhance serglycin (SRGN) levels." (PMID 35030969, 2022). "Serglycin has been demonstrated to be a marker of acute myeloid leukemia (AML)." (PMID 22777011, 2012). "Serglycin has been proposed as a selective biomarker for acute myeloid leukemia compared to Philadelphia chromosome-negative chronic myeloproliferative disorders since it is highly expressed only by leukemic blasts of patients with acute myeloid leukemia and not in acute lymphocytic leukemia." (PMID 24455486, 2014).
esophageal cancer (5 papers, 2020 to 2024). A primary or metastatic malignant neoplasm involving the esophagus. "Kaplan-Meier survival analysis of the TCGA esophageal carcinoma (ESCA) cohort showed that high expression of SRGN in tumor was associated with poorer survival." (PMID 33456569, 2021). "Finally, SRGN is involved in a paracrine loop between esophageal cancer cells and fibroblasts with the last ones to be activated creating a favorable microenvironment." (PMID 38672477, 2024). "In the study of esophageal cancer, the researchers identified midkine (MDK) as a novel partner of SRGN’s function." (PMID 38287411, 2024).
lung adenocarcinoma (5 papers, 2019 to 2025). A carcinoma that arises from the lung and is characterized by the presence of malignant glandular epithelial cells. "On the contrary, TTF‐1‐negative lung adenocarcinoma cell lines overexpressed serglycin, which was reported to upregulate the PD‐L1 expression." (PMID 35808895, 2022). "We have previously shown that SRGN in non-small cell lung cancer (NSCLC) promotes malignant phenotypes in a CD44-dependent manner and increased expression of SRGN predicts poor prognosis of primary lung adenocarcinomas." (PMID 31898491, 2020). "We have previously shown that SRGN is frequently overexpressed in lung adenocarcinomas, and functions in promoting NSCLC cell migration, invasion and stemness in a CD44-dependent manner." (PMID 31898491, 2020). "They reported that SRGN, TPM3, THBS1, HUWE1, and CCDC18 were enriched in lung adenocarcinoma extracellular vesicles." (PMID 30646616, 2019).
non-small cell lung carcinoma (5 papers, 2017 to 2024). A group of at least three distinct histological types of lung cancer, including non-small cell squamous cell carcinoma, adenocarcinoma, and large cell carcinoma. "Correspondingly, increased serglycin expression was shown to facilitate liver colonization by cancer cells in a patient-derived xenograft model of non-small-cell lung cancer (NSCLC) as well as to promote hepatocellular carcinoma metastasis to the bone." (PMID 32984308, 2020).
colorectal cancer (4 papers, 2020 to 2021). A primary or metastatic malignant neoplasm that affects the colon or rectum. "In lung and colorectal cancer, high expression and secretion of serglycin is associated with a poor clinical outlook and treatment resistance, while the knock-down of serglycin decreases tumor burden in vivo." (PMID 33330449, 2020).